KRAS (KRas proto-oncogene, GTPase)
Diseases named in the same sentence as KRAS in open-access papers (continued):
Sharing a sentence is not in itself a finding about the gene and the disease.
lung cancer (continued). "Thus, our findings provide rationale to co-target changes in the tumor microenvironment to prevent non-genetic mechanisms of resistance to KRAS inhibitors observed in roughly one-third of sotorasib-treated NSCLC patients, which will guide precision medicine for lung cancer patients." (PMID 39782689, 2025). "However, since G12D is the most common alteration of KRAS in PDAC these tumors are not amenable to treatment with G12C-specific agents, in contrast to many lung cancers and the 2% subset of pancreatic cancer patients carrying a G12C mutation that has been successfully hit." (PMID 36048281, 2022). "We further analyzed protein levels of YAP/TAZ in lung cancer cell lines, and the results showed that YAP and TAZ were not exclusively expressed in KRAS-mutant lung cancer cells, suggesting that other molecules apart from KRAS may regulate protein levels of YAP/TAZ." (PMID 34073318, 2021).
pancreatic cancer (2,348 papers, 1993 to 2026). "The most frequent driver mutation in pancreatic cancer is the G12D mutation in the KRAS gene, present in approximately 90% of the tumors." (PMID 42030284, 2026). "Similar dependency has been observed in KRAS mutated pancreatic cancer, where IGF1/AKT signaling supports tumor cell survival and dormancy after oncogene ablation." (PMID 41526435, 2026). "The KRAS oncogene, located on chromosome 12p, is one of the most frequently mutated genes in pancreatic cancer, and its mutations are activating, leading to abnormal production of the protein of the gene." (PMID 40507590, 2025). "With the emergence of targeted therapies for KRAS mutations, DNA damage repair deficiencies, and mismatch repair pathways, targeted treatment has become a research hotspot in pancreatic cancer." (PMID 40994638, 2025). "Mutated KRAS has been considered as a hallmark of pancreatic cancer since this protein is mutated in more than 90 % of PDACs." (PMID 39434498, 2025). "KRASG12D, the most prevalent KRAS mutation, is the most common mutation in pancreatic cancer, occurring in approximately 34% of the cases." (PMID 39810420, 2025). "Mutations in the KRAS oncogene are a key factor among the many genetic changes linked to the onset and spread of pancreatic cancer." (PMID 40157967, 2025). "The combination of ADM with an oncogenic mutation in the KRAS gene, the most commonly mutated gene in pancreatic cancer, drives the formation of neoplastic precursor lesions." (PMID 40156071, 2025). "TCR-001–transduced T cells specifically recognized endogenously processed and presented antigen and human pancreatic cancer cell lines with KRAS G12V mutation and HLA-A*11:01 expression." (PMID 39846249, 2025). "For instance, KRASG12C mutations are rare in pancreatic cancer (2–3% of all KRAS mutations) and CCA (8%) but represent the predominant KRAS mutation subtype in NSCLC (39–42%)." (PMID 41226789, 2025). "KRAS mutations are present in over 85% of pancreatic ductal adenocarcinomas, making their absence highly unusual for primary pancreatic cancer." (PMID 40656425, 2025). "Recent preclinical studies have identified a novel role for Galectin-1 in pancreatic cancer, acting not only as an extracellular signaling molecule but also as a nuclear regulator that sustains KRAS expression in cancer-associated fibroblasts." (PMID 40806185, 2025). "KRAS mutations have been a therapeutic target for lung, colorectal, and pancreatic cancer for decades." (PMID 40141193, 2025). "It should be highlighted that analysis of the mutational profile revealed that KRAS oncogene is mutated in approximately 93% of samples, with a subset of pancreatic tumors showing multiple variants in this gene, in addition to evidence of biallelic mutations." (PMID 40981070, 2025). "This study aimed to uncover colon and pancreatic cancers that shared transcriptional changes closely related to KRAS missense mutations." (PMID 40013338, 2025). "A hallmark of pancreatic cancer is the prevalence of cancerous mutations in the KRAS oncogene, which plays a key role in the development and maintenance of pancreatic tumors." (PMID 40612867, 2025). "A phase 1–2 study assessed the clinical outcomes of sotorasib treatment in 38 patients with pancreatic cancer, harboring a KRAS p.G12C mutation and receiving at least one prior treatment." (PMID 40124650, 2025). "First, KRAS mutations are found in approximately 20% of all patients with cancer, up to 94% of pancreatic cancers, and up to 45% of colon cancers." (PMID 39846249, 2025).
pancreatic cancer (continued). "Roughly 90% of individuals with pancreatic cancer have KRAS mutations, which are among the most frequent genetic abnormalities discovered in these patients." (PMID 40157967, 2025). "RAS mutations are thought to make up 20% of all cancers, with activating KRAS mutations alone comprising 35% of lung, 45% of colorectal, and 90% of pancreatic cancers." (PMID 39899215, 2025). "It is relevant to indicate that all the pancreatic cancer cell lines used in the present study carry KRAS codon 12 mutations." (PMID 40410803, 2025). "The KRAS-G12D mutation induces hyperactivation of the SUMOylation pathway in pancreatic cancer cells." (PMID 41463025, 2025). "In ongoing research, we are trying to identify additional TCRs targeting KRAS mutations in human pancreatic cancer patients with other KRAS mutations or HLA expression using our sequential in vitro stimulation approach." (PMID 39846249, 2025). "The KRAS oncogene, found in about 90% of pancreatic cancers, serves as a pivotal mutation driving the aggressiveness of the disease." (PMID 40895848, 2025). "These peptides cause cytotoxic effects, particularly in KRas mutant pancreatic cancer cells (PANC‐1) in which they also alter downstream signaling of Ras proteins." (PMID 40270247, 2025). "While KRAS mutations are less frequent in melanoma compared to colorectal or pancreatic cancers, their impact on progression and therapy resistance is increasingly recognized." (PMID 40652269, 2025). "Engineered bEVs also act as RNA delivery vehicles; encapsulation of siRNAs targeting oncogenic KRAS mutations has suppressed tumor growth in pancreatic cancer models, suggesting translational potential for KRAS-driven LC." (PMID 41463196, 2025). "Kirsten RAS (KRAS) mutation occurs in 95% of pancreatic cancers, however, direct targeting of KRAS represents a major challenge in pancreatic cancer therapy." (PMID 40708975, 2025). "While our study demonstrates that the Do‐Cy nanocomplex is preferentially internalized by KRAS‐mutant pancreatic cancer cells through elevated macropinocytosis, the underlying mechanism of macropinocytosis is not unique to PCCs." (PMID 39951277, 2025). "The most common activating mutation that occurs in approximately 65.4% of pancreatic cancer cases is KRAS mutation." (PMID 40230862, 2025). "In pancreatic cancer, increased KRAS gene dosage is associated with early tumorigenesis, tumor progression, and increased incidence of metastasis in vivo." (PMID 39412982, 2025). "Second, this study was limited to a single KRAS G12C-mutated pancreatic cancer cell line: MIA PaCa-2." (PMID 40806294, 2025). "This study aims to construct an iRGD-modified BiTE-directed T-cell therapeutic approach to enhance the treatment efficacy against KRAS G12V-mutated pancreatic cancer." (PMID 41472736, 2025). "Over 90 percent of pancreatic cancers harbor a somatic KRAS mutation; furthermore, these mutations appear to occur very early in pancreatic carcinogenesis, as indicated by their presence in noninvasive precursors." (PMID 40507590, 2025). "When stratified by isoform, KRAS mutations were observed in approximately 80% of pancreatic cancers and 54% of bowel cancers." (PMID 40970755, 2025). "KRAS, the most commonly altered gene in pancreatic cancer, was mutated in 22 (85%) of the 26 cell lines in the present study." (PMID 39972450, 2025). "Next, we queried four databases through the cBioPortal platform (MSK-IMPACT, CTPAC, TCGA, ICGC) and reviewed GNAS and KRAS mutation data of 2759 pancreatic cancer patients." (PMID 40002298, 2025).
pancreatic cancer (continued). "KRAS mutations occur in over 90% of pancreatic cancers, with G12D (37.0%), G12V (28.2%), G12R (12.7%), and G12C (2.7%) being the most frequent subtypes." (PMID 41463025, 2025). "Genetically, KRAS mutations initiate the development of pancreatic cancer, and more than 90% of PanINs harbor KRAS mutations." (PMID 39820281, 2025). "For instance, in pancreatic cancer, exosomal KRAS mutations have been proposed as liquid biopsy alternatives for early detection, as they capture the molecular landscape of tumor evolution." (PMID 40149276, 2025). "For proof-of-concept demonstration, we used SPEAR to detect the KRAS gene mutation in pancreatic cancer." (PMID 40093900, 2025). "Three KRAS‐dominant missense mutations, G12, G13, and Q61, have implications for both colorectal and pancreatic cancers." (PMID 40013338, 2025). "Reducing dietary BCAA levels significantly suppressed pancreatic cancer development in mouse models with KRAS mutations." (PMID 40437561, 2025). "PDEδ critically regulates oncogenic KRAS membrane localization and signal transduction, with KRAS mutations driving ~30% of lung, 45% of colorectal, and 90% of pancreatic cancers." (PMID 40724826, 2025). "To shed light on the impact of KRAS protein level in pancreatic cancer, we compared the KRAS protein level, KRAS mRNA expression level and KRAS mutation status in PDACs and investigated their individual and combined associations with survival." (PMID 40596921, 2025). "Molecularly, pancreatic cancer is characterized by nearly universal Kirsten Rat Sarcoma Viral Oncogene Homolog (KRAS) mutations (>90%), and high expressions of multidrug resistance genes." (PMID 41154706, 2025). "KRAS p.G12D is the most frequent KRAS alteration, accounting for 40–45% of KRAS mutations in pancreatic cancer and 25–45% in mCRC." (PMID 41153346, 2025). "Although targeting KRAS in pancreatic cancer is an attractive strategy because of the high frequency of mutations compared to that in other cancers, the development of KRAS inhibitors has remained unsuccessful for decades." (PMID 39400496, 2025). "The results show that after CaaX‐1 treatment, not only KRas expression and signaling are specifically altered in mutated pancreatic cancer cells, but also plasma membrane localization of KRas is affected." (PMID 40270247, 2025). "Oncogenic mutations in KRAS drive common metabolic changes across colorectal, lung, and pancreatic cancers, which facilitate tumor survival, growth and immune evasion." (PMID 40707783, 2025). "Oncogenic KRAS mutations are common in cancer and almost ubiquitous in pancreatic cancer, with mutations detected in around 95% of patients." (PMID 39412982, 2025). "Acute KRAS silencing in KRAS‐mutant pancreatic cancer cells by RNAi or CRISPR caused cell cycle arrest, apoptosis, and reduction of anchorage‐independent proliferation in vitro, as well as reduced tumour growth and metastasis in xenograft models." (PMID 39434498, 2025). "Numerically better disease control rates (50% vs. 20%) and median survival (5.8 months vs. 3.9 months) were observed for KRAS wild-type (WT) vs. KRAS-mutated (MUT) pancreatic cancers." (PMID 40507311, 2025). "Mutations in KRAS lead to uncontrolled cell growth and contribute significantly to the progression of pancreatic cancer." (PMID 40567499, 2025).
pancreatic cancer (continued). "Pancreatic cancers with KRAS mutations show dysregulated BCAA catabolism, leading to the accumulation of BCAA-derived acetyl-CoA, which significantly affects disease onset and progression." (PMID 40437561, 2025). "It has been demonstrated that pancreatic cancer cells harbor early KRAS mutations and this is associated with an immunosuppressive environment in animal models." (PMID 40124650, 2025). "In colorectal and pancreatic cancers, additional co-mutations in KRAS (non-G12C alleles), EGFR, PIK3CA, BRAF, and MAP2K1 are frequently detected at baseline and are linked to primary resistance, underscoring the importance of comprehensive NGS at diagnosis." (PMID 40940900, 2025). "Their research showed that partial or complete ATM deficiency interacts with the KRAS gene to promote highly metastatic pancreatic cancer and also leads to permanent DNA damage in precancerous lesions and primary tumors." (PMID 41155399, 2025). "The 323965-272-R-J2 pancreatic cancer also harbors the KRAS G12C mutation, while the 349418-098-R non-small-cell line is KRAS wildtype." (PMID 40761343, 2025). "KRASG12D mutation is a prevalent gain-of-function mutation that drives pancreatic cancer tumorigenesis, but the underlying mechanisms that promote KRAS-induced cell proliferation and tumor formation remain elusive." (PMID 41391757, 2025). "Patients with the KRAS mutation p.G12C in their pancreatic tumor have now the opportunity to get specific p.G12C inhibitors (sotorasib and adagrasib), which are FDA approved for non-small cell lung cancer and have shown promising results for pancreatic cancer." (PMID 40596921, 2025). "KRAS is mutated in the early stages of pancreatic cancer development; constitutively active KRAS is sufficient for the development of PDAC." (PMID 39400496, 2025). "Studies on genetically engineered mouse models found that the formation of pancreatic cancer involved a combination of pancreatitis and KRAS gain-of-function mutation." (PMID 41391757, 2025). "Our study identifies how oncogenic KRAS/ERK signaling suppresses GATA6 to cause dedifferentiation in pancreatic cancer." (PMID 41329526, 2025). "Sotorasib has been investigated in clinical trials for the treatment of KRAS G12C-mutated pancreatic cancer." (PMID 40806294, 2025). "These mutations hinder the normal function of KRAS, impacting various signaling pathways and contributing to the poor prognosis associated with pancreatic cancer." (PMID 40895848, 2025). "More than 90% of pancreatic cancers have mutations in the KRAS gene, and it has been noted that cancers with mutant KRAS are susceptible to ferroptosis." (PMID 39858464, 2025). "Although no “universal marker” emerged, several miRNAs such as miR-21, 155, 223, and 34a were identified as both more frequently reported and mechanistically linked to critical pathways in pancreatic cancer, including KRAS, NF-kB, and PI3K/AKT." (PMID 41189938, 2025). "Among these mutants, KRASG12D accounts for approximately 40% of all KRAS mutation in pancreatic cancer, making it the most prevalent subtype." (PMID 41391757, 2025). "We focused on human pancreatic cancer patients with KRAS G12V mutation and HLA-A*11:01 expression detected by whole-exome sequencing." (PMID 39846249, 2025).